IL6 (interleukin 6)
Diseases named in the same sentence as IL6 in open-access papers (continued):
Sharing a sentence is not in itself a finding about the gene and the disease.
tumor (continued). "EBV latent membrane protein 1 (LMP1) was reported to increase the production of IL-1β, IL-6, and GM-CSF in NPC tumor cells, which finally promoted MDSC in the tumor microenvironment." (PMID 33290259, 2020). "M1 macrophages are conventionally activated macrophages that secrete pro-inflammatory cytokines such as IL-1β, IL-6, IL-8, IL-18, TNF-α, and IFN-γ, and exert an anti-tumor effect." (PMID 32993787, 2020). "Thereafter, activated CTLs recognize tumor cells and induce tumor regression by secreting cytokines, including interferon-γ (IFN-γ), tumor necrosis factor-α and interleukin-6." (PMID 32317755, 2020). "Increased levels of IFN-γ, IL6, ITAC were also observed in the sera of tumor-bearing hu-BLT mice injected with OC-expanded NK cells." (PMID 33230147, 2020). "In particular, IL‐6 is the primary mediator of inflammation, which is the key to trigger the JAK2/STAT3 pathway, and plays a crucial role in tumor cell proliferation and invasiveness." (PMID 32677756, 2020). "Further, IL-6 triggers the activation of the IL-6/JAK/STAT3 pathway which generally enhances proliferation, survival, invasiveness and metastasis of tumor cells, while strongly suppressing the antitumor immune response." (PMID 32899119, 2020). "In return, elevated IL6 in cell supernatants induces EMT, and the invasion and metastasis of tumor cells via signal transducer and activator of transcription 3 (STAT3) signaling." (PMID 32308766, 2020). "TAMs are known to secrete anti-inflammatory cytokines such as IL-6, IL-10 and TGF-β, thereby enhancing immunosuppression in tumor microenvironment, leading to promotion of GBM cell growth and angiogenesis." (PMID 32765498, 2020). "Growth factors, cytokines, and enzymes (e.g., TGF-β, IL-6, NOS2, and COX2) are known to stimulate the free radical species (reactive oxygen, ROS, and nitrogen, NOS, species) production, which promote tumor development and progression." (PMID 32423132, 2020). "Tumor cells-macrophage co-culture increases expression of IL10, IL12, IL6, TNF, CCL5, CCL22, and CSF1 in macrophages, thereby inducing M2-like polarization." (PMID 32219066, 2020). "In C26 tumor-bearing BALB/c mice, involvement of myokines was further indicated as increased muscle IL-6, IL-6R, and myostatin expression accompanied muscle wasting in these mice." (PMID 33329046, 2020). "This trend is also consistent with the IL-6 levels measured in the tumor mass, however, the differences of TNF-α level in the tumor mass between mouse groups receiving 2 and 8 Gy irradiation are marginal." (PMID 32541769, 2020). "In the context of this article, it should be mentioned that these substances reduce the actual levels of IL-6 and TNF-α, factors known for their supporting role in tumour growth and spread." (PMID 33114676, 2020). "Combined blockade of IL6 and PD-1/PD-L1 signals increases the expression of T cell-attracting chemokines and facilitates IFN-γ-producing CD4 T cell infiltration into tumor tissues, producing a synergistic anti-tumor effect." (PMID 33344447, 2020). "In this study, immunohistochemistry was used to analyze the expression of inflammatory factors, such as COX-2, iNOS, IL-6,IL-8,MIP-3α,TGF-β1 and VEGF, in the transplanted tumor tissues." (PMID 32095158, 2020). "Only SFV4-infected tumor cells consistently induced DCs to secrete Th1 cytokines (IFN-γ, IL-12, TNF-α), Th2 cytokines (IL-4, IL-13), proinflammatory cytokines (IL-6, IL-8, IL-1β,) and anti-inflammatory cytokine (IL-10)." (PMID 31969562, 2020). "Downstream of IL-6 signaling, NF-κB has also been shown to induce epithelial-mesenchymal transition (EMT), which then promotes tumor cell migration." (PMID 33143283, 2020). "Thereafter, IL-6 activates the signal transducer and activator of transcription 3 (STAT3) pathway in immune cells, stromal cells and tumor cells, which supports immune escape of cancer cells." (PMID 32230983, 2020). "For instance, the high levels of IL-1β, IL-6, and CXCL2 in the tumor microenvironment favor MDSC expansion." (PMID 32632113, 2020).
tumor (continued). "In the NF-κB signaling pathway, NF-κB modulates many crucial genes in macrophages and many tumor-promoting genes, such as VEGF, IL-6, TNF-α, and COX2." (PMID 32850861, 2020). "Metformin also selectively acts against CSCs by targeting EMT, blocking the IL-6/STAT3 axis or decreasing EMT transcriptional factors, and by increasing tumor sensitivity against other current therapies; therefore, it has been included in clinical trials." (PMID 33059744, 2020). "Several factors, such as interleukins (e.g., IL-1, IL-6, IL-8), tumor necrosis factor type α (TNF-α), and others are produced by tumor cells and activated by immune cells in tumor milieu." (PMID 32121320, 2020). "Up-regulated exosomal miR-let-7i in tumor-derived exosomes (TEX) can be taken up by mDCs, resulting in changes in intracellular levels of IL-6, IL-17, IL-1b, TGFbeta, SOCS1, KLRK1, IFNγ, and TLR4, thereby suppressing the immune response." (PMID 32299469, 2020). "During chronic inflammation, the cytokines tumor necrosis factor (TNF-α), interleukin 6 (IL-6), transforming growth factor β (TGF-β), and interleukin 10 (IL-10) have been shown to be involved in tumor induction, proliferation, and metastasis." (PMID 33023215, 2020). "There is evidence that neutrophils and other immune cells, such as macrophages, have the capability to secrete cytokines and tumor growth promoting factors, including VEGF, HGF, IL-6, IL-8, matrix metalloproteinases, and elastases." (PMID 32325965, 2020). "IL-6 and TNF-α, two critical inflammatory mediators involved in the stimulation of tumor microenvironment, were measured in both serum and colon extracts." (PMID 32664279, 2020). "We also examined the relationship between IL-6 and PD-L1/PD-L2 positive CD45+CD14+ inflammatory cell (MO/MA) levels in three OC environments (TME): peripheral blood (PB), PF, and tumor (TT) and their clinical and prognostic relevance in OC patients." (PMID 33062717, 2020). "NO is reported to regulate the expression of various cytokines, growth factors and chemokines, including IL-6, IL-10, IFNγ, TGFβ, M-CSF, VEGF and MCP-1, which are important in tumor growth and metastasis." (PMID 32509271, 2020). "For example, Th17 polarized cells in cell culture with TGFβ, IL6, and anti-IFN-γ antibody (preventing Th1 differentiation) mediated effective tumor eradication and a survival advantage in a murine melanoma model." (PMID 33381115, 2020). "Cytokines such as Interleukin 6 (IL-6), Tumor Necrosis Factor alpha (TNF-α), Interleukin- 1β (IL-1β) and Interleukin 10 (IL-10), which are released peripherally and in the tumor microenvironment, can act locally in reciprocal signaling interactions." (PMID 33126617, 2020). "MCs through releasing IL-1, IL-4, IL-6, and TNF-α can actively participate in the elimination of tumor cells and rejection of tumors." (PMID 31256327, 2020). "IL-6, an activator of STAT3, frequently elevated in RCC, is known to induce tumor progression and metastasis across tumor types, and is sufficient to induce skeletal muscle STAT3 activation leading to muscle wasting resulting cachexia." (PMID 32560494, 2020). "FKBPL-based therapy can (i) dually target angiogenesis and CSCs, (ii) target the CD44/STAT3 pathway in tumours and (iii) is effective in highly vascularised HGSOC tumours with low levels of IL-6." (PMID 31772325, 2020). "TANs have been shown to induce genetic instability through the release of reactive oxygen species (ROS) and to produce tumor necrosis factor, IL-1, IL-6 and VEGF, which contribute to tumor proliferation and immune escape." (PMID 32711491, 2020). "Hh signalling can be triggered by an array of factors in the tumor microenvironment, such as transforming growth factor- (TGF-) β, tumor necrosis factor- (TNF-) α, and interleukin (IL)-6." (PMID 32211043, 2020). "When both neutralizing antibodies to IL-6 and HGF were simultaneously added to the CAF-CM, the invasive ability of tumor cells was most strongly inhibited." (PMID 32792856, 2020).
tumor (continued). "That also correlated with the increased production of VEGF, IL-6, and TGF-β1, the effectors of tumor angiogenesis." (PMID 33015029, 2020). "In a study addressing not only TNFα but also IL-1β, the two cytokines were shown to increase tumor cell proliferation in a metastasis-suppressed model of a TNBC cell line and in combination with IL-6 and CXCL8 also of luminal-A cells." (PMID 33585241, 2020). "Interleukin (IL)-6 and YKL-40 are pleiotropic biomarkers present in the tumor microenvironment and involved in immune regulation." (PMID 32363159, 2020). "IL6 trans-signaling enhances both E- and P-selectin interactions and ICAM1 dependent T-cell transmigration on tumor vessels." (PMID 33381115, 2020). "Similar to what happens with IL-6, HAS2 overproduction by tumor cells has also been shown to induce BC stemness independently of macrophages through the induction of a transforming growth factor-beta (TGF-β)/Twist-driven EMT program." (PMID 33371274, 2020). "From GOG 218, which enrolled 1248 patients, tumor microvessel density was evaluable on 980 FFPE samples (78.5% of the intended treatment population), and plasma IL6 on 751 plasma samples collected at baseline (60% of enrolled patients)." (PMID 32272732, 2020). "Even after incubation with IL-6, the concentration of EpCam+CD44+CD24– tumor stem cells was 1.33 times higher in patient St23784/17 than patient Ti41749/17." (PMID 32523653, 2020). "The NF-κB pathways are important during cytokine activation as they regulate tumor cell survival during early tumor promotion and induce the transcription of genes for proinflammatory cytokines, such as TNF-α and IL-6." (PMID 32156252, 2020). "The pathways engaged in the synthesis of IL-6, IL-1, IL-12p70, and TNF-α in DCs were affected by HHP-treated tumor cells." (PMID 32340275, 2020). "The presence of tumor infiltrating Th-17 cells induces the expression of G-CSF by CAFs and increased production of IL-6 and SDF1 by CAFs and tumor cells, allow the recruitment of MDSCs." (PMID 32775327, 2020). "In this study, immunohistochemical expression of TNF-α, IL-6, IL-1β, and IL-2 in GEP-NENs was evaluated and correlated with the proliferation, tumor grade, tumor, node, metastasis (TNM), and outcomes." (PMID 32156252, 2020). "This was thought to be related, in part, to the decreased production of IL-10, IL-6, TGF-β and VEGF, and the alleviation of the tumor immunosuppressive microenvironment." (PMID 32532126, 2020). "Compared to the control group, the content of anti-tumor immunity-related cytokines IFN-γ, TNF-a, IL-2, and IL-5 increased, while IL-6, related to inhibiting anti-tumor immunity, decreased in the TME." (PMID 32802195, 2020). "M1 macrophages typically express proinflammatory cytokines (e.g. IFN-β, IL-12, TNF, IL-6, and IL-1β) and MHC class II molecules, and carry a therapeutic benefit, promoting anti-tumor activities." (PMID 32788720, 2020). "IL-17 acts directly on HCC cells, inducing AKT-dependent IL-6/JAK2/STAT3 activation and tumor progression." (PMID 33718121, 2020). "Each tumor cell type is distinguished by the involvement of typical biological factors (e.g., DKK-1, Wnt, and PSA in PC and IL-6 plus VLA-4/VCAM-1 pathway in MM)." (PMID 33224935, 2020). "They exert pro-inflammatory, anti-tumor, and anti-microbial functions, releasing high levels of pro-inflammatory cytokines, such as TNF-α, Interleukin-6 (IL-6), Interleukin-1β (IL-1β), and Nitric Oxide Synthase (iNOS)." (PMID 33374151, 2020). "The CD68, IL-6, and TNF-α expression in tumor cells was significantly higher in FOBT-positive patients than in FOBT-negative patients (all p<0.05)." (PMID 33643891, 2020). "IL-6 promotes angiogenesis via MMP-9 activation which induces release of VEGF from cultured ECs and tumor cells and also induces expression of VEGF-R2 (KDR) on cultured ECs." (PMID 33109684, 2020).
tumor (continued). "Since IL6 upregulates SOCS-1, which is a negative regulator of JAK-STAT signaling cascade, we next examined the methylation pattern of SOCS-1 gene promoter in tumor tissues." (PMID 33569347, 2020). "IDO1 is also involved in promoting tumor neovascularization by modulating the expression of interferon-γ (IFN-γ) and IL-6." (PMID 32486450, 2020). "Afterward, we observed that the tumor growth and metastasis were promoted by the upregulation of DLGAP1-AS1, while were inhibited after overexpression of miR-26a/b-5p or silencing of IL6." (PMID 31949128, 2020). "Tumor-induced factors, including prostaglandin E2 (PGE2), IL-6, IL-10, IL-1β, and transforming growth factor beta (TGF)-β have been shown to result in the recruitment and activation of MDSCs in the TME in malignant tumors." (PMID 33384962, 2020). "Our results suggest that increased RCC2 expression stimulates tumor growth by upregulating IGF1, TWIST1, and IL-6 expression." (PMID 32565805, 2020). "In comparison, patients with low IL-6 and low MMP9 had the best outcomes with respect to tumor recurrence, surgery, or death." (PMID 32545247, 2020). "IDO and TDO are highly expressed in tumor cells and can promote the recruitment of Tregs in the TME and induce immunosuppression via increased secretion of the immunosuppressive factors IL-6, IL-10, and TGF-β,93–95 which can help tumors achieve TIE." (PMID 32561709, 2020). "However, histamine might have a tumor‐suppressing effect when combined with IL‐6." (PMID 32547744, 2020). "mRNA levels of inflammatory cytokines in tumor tissue of irradiated mice were also modulated by DEX, showing a pronounced decrease for IL-6 and TNFα." (PMID 32325715, 2020). "Herein, we explored the relationship between IL-6 and CD73 in the TME of NPC, especially the potential contribution of MSC-derived IL-6 and CD73 expression to tumor growth and chemotherapeutic resistance in NPC." (PMID 32127934, 2020). "A previous study showed that distinct subsets of myeloid suppressor cells correlate with plasma IL-6 and IL-10, and impaired response to IFN-α to promote anti-tumour immunity in patients with gastrointestinal malignancies." (PMID 32973748, 2020). "In turn, secreted IL-6 activates STAT3, which increases the level of expression of genes inducing tumor progression and metastasis." (PMID 32148497, 2020). "IL-6 produced by primary tumor stroma induced STAT3 signaling in 80–90% hepatocytes, compared to activation in 2% hepatocytes in non-tumor bearing mice." (PMID 32230953, 2020). "These transcription factors were modulated to produce several important tumor growth-promoting cytokines, including TNF-a, IL- 1β, and IL-6." (PMID 32716955, 2020). "For example, a positive FFL IL-6/JAK/Stat3, in which IL-6 activates JAK and STAT3 was involved in tumor proliferation, tumor microenvironment shaping, and metastasis." (PMID 31537905, 2020). "Overall, our results suggest that apart from its known tumor suppressor role, Mir34a also has an anti-inflammatory role in the pancreas by downregulating TNFA and IL6." (PMID 32541781, 2020). "Tumor-related humoral factors, such as granulocyte colony-stimulating factor (GCSF), interleukin-1 (IL-1), and interleukin-6 (IL-6), stimulate platelet production." (PMID 32226498, 2020). "As for the IL6‐JAK‐STAT3 signaling, studies showed it involved in tumor growth, metastasis, and the immune escaping." (PMID 33030278, 2020). "Cytokines, like IL-10, IL4, IL-6, and TGF-β, released by these cells can inhibit both innate and adaptive immunity and can also directly promote tumor progression." (PMID 32595757, 2020). "In vivo study further demonstrated that the mice bearing Raji cells treated with ssCART-19 cells showed significant lower IL-6 levels in serum than those treated with regular CART-19 cells, but comparable anti-tumor efficacy between the animal groups." (PMID 32523801, 2020).
tumor (continued). "Research on the detailed mechanisms of this process showed that CCc proliferation occurs through an IL-6/JAK2/STAT3-dependent mechanism and VEGF-induced tumor angiogenesis." (PMID 32429087, 2020). "In fact, many studies have shown that various cytokines such as tumor TNF-α and IL-6 are involved in the pathogenesis of CHD." (PMID 32508942, 2020). "Further experiments showed that ALDH3A1 acts as a tumor suppressor gene and inhibits EMT via IL-6/STAT3 signaling pathway in OSCC cells." (PMID 32201532, 2020). "Tumor grade, serum CRP, and IL-6 levels in patients exhibiting a high expression of both IL-6 and IL-6R were high." (PMID 32138303, 2020). "This study examined cytokine levels and found that the levels of inflammation-related cytokines, such as IL-6, IL-1β, and TNF-α, were decreased in FLP-treated MO mice in the tumour tissues compared to those of MO mice." (PMID 32308722, 2020). "In the tumor microenvironment, tumor stroma surrounding PCa cells is enriched in fibroblasts that secrete AR-activating factors, such as EGF, FGF-7/KGF, IGF-1, and IL-6." (PMID 31484364, 2019). "In both OSCC animal models, SCNE significantly depressed circulating pro-cancer inflammatory cytokines (host and tumor-secreted) including NFkB, COX2, IL-1, IL-6, TNFα, and IFNγ." (PMID 31572681, 2019). "First hypoxia, a distinctive feature of tumor, stimulates a release of VEGF and IL-6 from mast cells." (PMID 30680411, 2019). "The persistent production of pro-inflammatory cytokines such as IL6, tumor necrosis factor (TNF) and IL1 within the tumor and its microenvironment plays a key role in mediating the tumor-promoting effect of inflammation." (PMID 31878932, 2019). "This study demonstrates that activation of IL-6/STAT3 regulates OCT4 expression through DNMT3b, which is an indicator of early tumor recurrence and poor prognosis of HCC." (PMID 31771617, 2019). "On the other hand, TAMs can promote the secretion of tumor growth-promoting factors such as TNF-α, IL6, TGF-β, PDGFR, and VEGFR, among others." (PMID 31569444, 2019). "Tumor progression and CSC survival can be regulated by the cytokines IL-6 and IL-8 in an autocrine or paracrine manner." (PMID 31480284, 2019). "A recent study showed that IL-6 was responsible for both promoting oncogenesis when secreted from CAFs and CAF activation when secreted from tumour cells." (PMID 31308358, 2019). "Pancreatic tumor-bearing mice receiving dCAR-T cells released higher levels of cytokines, including IL-2, IL-6, IFN-λ and TNF-α, and showed a marked reduction in tumor growth compared to controls receiving CAR-T cells alone." (PMID 30987642, 2019). "Under both experimental conditions, disrupting endothelial ICAM-1/tumor LFA-1 interaction results in a dramatic reduction in the secretion of IL-1β, IL-6, PGE2 and TNFα into the co-culture supernatant." (PMID 31511625, 2019). "STAT3 can be activated by IL-6 and its persistent activation contributes to CRC tumor growth and proliferation." (PMID 31864341, 2019). "Chronic inflammatory conditions promote myeloid cell recruitment to the tumor site where tumor-derived cytokines such as IL-10, TGF-β, GM-CSF, IL-6 initiate their immunosuppressive properties." (PMID 31555270, 2019). "While IL-6 and TGF-β favor tumor growth, TNF-α, osteopontin, matrix metalloproteases (MMPs), and IL-6 supports invasion and metastasis." (PMID 31849997, 2019). "Various mechanisms appear to be involved, including the presence of tumour growth inducing inflammation and plasma CRP, as well as the tumours directly producing various inflammatory cytokines, including CRP, IL-6 and IL-8, which in turn induce hepatic CRP." (PMID 30662766, 2019). "Synbiotics-treatment suppressed DSS-induced expression of IL-6, STAT-3, COX-2, and TNF-α gene transcripts in normal colonic epithelium, indicating the possibility of suppressing tumor development." (PMID 31242213, 2019).